LINC00943 (long independently transcribed non-coding RNA 943)
Gene: Long non-coding RNA gene on chromosome 12 (126,723,412 to 126,749,027, forward strand). Ensembl gene ENSG00000189238.
Diseases named in the same sentence as LINC00943 in open-access papers:
LINC00943 is named in the same sentence as 8 diseases in open-access papers, as found by Europe PMC text mining. Sharing a sentence is not in itself a finding about the gene and the disease. The quoted sentences say what the papers report.
breast carcinoma (2 papers, 2022 to 2023). "Taking LINC00943 as the first example, a ceRNA theory article for breast cancer found that LINC00943 is elevated in the high CD8 T-cell group compared with the low CD8 T-cell group, proving its close relationship with CD8 T cells." (PMID 37275855, 2023). "There is not much research describing the roles of LINC00943, LINC01146, AC092718.4, and AC005332.4 in breast cancer." (PMID 35756601, 2022).
gastric cancer (2 papers, 2021 to 2024). A primary or metastatic malignant neoplasm involving the stomach. "The upregulation of LINC00943 regulates the proliferation of gastric cancer cells and sensitivity to chemotherapy, and is also associated with poor prognosis in gastric cancer patients." (PMID 39469643, 2024). "A recent study shows that LINC00943 is upregulated in gastric cancer." (PMID 34958632, 2021).
cutaneous melanoma (1 paper, 2020). A primary melanoma arising from atypical melanocytes in the skin. "In addition, MALAT1 and LINC00943 may be independent risk factors for the prognosis of patients with cutaneous melanoma and might become predictive molecules for the long-term treatment of melanoma and potential therapeutic targets." (PMID 32993558, 2020). "MALAT1, LINC00943, and LINC00261 were selected as hub genes and are responsible for the tumorigenesis and prognosis of cutaneous melanoma." (PMID 32993558, 2020). "Further studies are required to validate the role of MALAT1, LINC00943 and LINC00261 in cutaneous melanoma." (PMID 32993558, 2020). "MALAT1, LINC00943, and LINC00261 may be closely related to tumorigenesis in cutaneous melanoma." (PMID 32993558, 2020).
lung squamous cell carcinoma (1 paper, 2024). "Therefore, this study explored the prognostic role of LINC00943 in lung squamous cell carcinoma (LUSC) and understood its impact on the development of LUSC." (PMID 38627774, 2024).
melanoma (1 paper, 2020). A malignant, usually aggressive tumor composed of atypical, neoplastic melanocytes. "In addition, MALAT1 and LINC00943 may be independent risk factors for the prognosis of patients with this condition and might become predictive molecules for the long-term treatment of melanoma and potential therapeutic targets." (PMID 32993558, 2020). "Thus, the expression of MALAT1, LINC00943 and LINC00261 is increased in melanoma and may be responsible for the tumorigenesis of melanoma." (PMID 32993558, 2020).
pulpitis (1 paper, 2023). Inflammation of the dental pulp. "According to previous studies, LINC00943 and PDK4 may reveal the correlation between ferroptosis and pulpitis; however, their interaction has not yet been discussed." (PMID 37275855, 2023).
cancer (3 papers, 2020 to 2025). A tumor composed of atypical neoplastic, often pleomorphic cells that invade other tissues. "Interestingly, wo found that XIST, SNHG14, NEAT1, LINC00943, KCNQ1OT1 have pro-tumor functions in various cancers but DHRS4-AS1 can inhibit tumor development." (PMID 40015977, 2025). "Therefore, we suspected that LINC00943, LINC00174, DSCAM-AS1, MAGI1-IT1, MIR4458HG and LINC01133 may have similar regulatory roles in the proliferation and differentiation of stromal and neutrophil cells as those in the proliferation and differentiation of cancer cells." (PMID 38919957, 2024).
tumor (3 papers, 2020 to 2025). "The results showed that the expression of MALAT1, LINC00943 and LINC00261 was significantly higher in the tumour tissues than in the healthy tissues (p = 0.0243, p = 0.0005, p < 0.0001, respectively)." (PMID 32993558, 2020). "Additionally, the expression of MALAT1, LINC00943 and LINC00261 was significantly higher in the tumour tissues than in the adjacent normal tissues (p = 0.0002, p < 0.0001, p < 0.0001, respectively)." (PMID 32993558, 2020). "However, the expression and function of LINC00943 in LUSC, and whether it can play a role in affecting tumor progression have not been documented." (PMID 38627774, 2024).